LY86 (lymphocyte antigen 86)
Description:
May cooperate with CD180 and TLR4 to mediate the innate immune response to bacterial lipopolysaccharide (LPS) and cytokine production. Important for efficient CD180 cell surface expression (By similarity).
Synonyms: MD1; MD-1; dJ80N2.1; MMD-1
Tractability: Antibody: UniProt places it where antibodies can reach, with medium confidence; UniProt predicts a signal peptide or a membrane-spanning region; its Gene Ontology location is reachable by antibodies, with medium confidence. PROTAC: its protein half-life has been measured.
Gene: Protein-coding gene on chromosome 6 (6,588,108 to 6,654,983, forward strand). Ensembl gene ENSG00000112799.
Subcellular location: Secreted, extracellular space
Pathways (Reactome):
Immune System: Toll Like Receptor 4 (TLR4) Cascade
Gene Ontology:
Molecular function: protein binding
Biological process: positive regulation of lipopolysaccharide-mediated signaling pathway; innate immune response; immune response
Cellular component: extracellular region
Genetic constraint (gnomAD): Loss-of-function variants: 11 observed, 13.03 expected, observed/expected ratio (o/e) 0.84, 90% interval 0.53 to 1.39. The upper end of that interval is the gene's LOEUF score, 1.39, which puts it in group 5 of 6, group 1 being the genes least tolerant of losing a copy. Missense variants: 140 observed, 147.9 expected, observed/expected ratio (o/e) 0.95, 90% interval 0.82 to 1.09. Synonymous variants: 55 observed, 56.26 expected, observed/expected ratio (o/e) 0.98, 90% interval 0.79 to 1.22.
Homologues: Orthologues: chimpanzee LY86 (99% identical), macaque LY86 (96% identical), guinea pig LY86 (71% identical), rabbit LY86 (69% identical), mouse Ly86 (67% identical), rat Ly86 (67% identical), dog LY86 (55% identical), pig LY86 (55% identical), zebrafish ly86 (30% identical).
Diseases named in the same sentence as LY86 in open-access papers:
LY86 is named in the same sentence as 89 diseases in open-access papers, as found by Europe PMC text mining. Sharing a sentence is not in itself a finding about the gene and the disease. The quoted sentences say what the papers report.
Obesity (16 papers, 2013 to 2024). Accumulation of substantial excess body fat. "LY86, also known as MD1, has been implicated in various pathophysiological processes including inflammation, obesity, insulin resistance, and immunoregulation." (PMID 38822281, 2024). "DNA methylation of the lymphocyte antigen 86 (LY86) gene was reported to be associated with obesity, and insulin resistance through a multi-stage cross-sectional study." (PMID 31849831, 2019). "Methylation of the Ly86 gene has been associated with obesity, insulin resistance, and inflammatory markers." (PMID 28575045, 2017). "Polymorphism in the MD-1 (LY86) locus was found to be associated with obesity and body fat distribution in certain populations in unbiased genome wide studies." (PMID 26555723, 2015). "However, only a limited subset of these loci has shown consistent associations with obesity development after rigorous multiple corrections or validation in different populations, for instance, lymphocyte antigen 86 (LY86) methylation and single-minded homolog 1 (SIM1) methylation." (PMID 40302954, 2024). "Higher methylation of the lymphocyte antigen 86 (LY86) gene and subsequent decrease in the expression of its encoding protein MD-1, was found to be significantly correlated with obesity, IR, and inflammatory markers in two genome-wide DNA methylation panels." (PMID 35603204, 2022).
cardiac hypertrophy (11 papers, 2015 to 2024). "Recent studies have demonstrated that the negative role of LY86 in various cardiac pathologies such as pressure overload-induced cardiac and electrical remodeling and high-fat diet-induced atherosclerosis; furthermore, LY86 deficiency exacerbates cardiac hypertrophy." (PMID 38822281, 2024).
Insulin resistance (10 papers, 2013 to 2024). Increased resistance towards insulin, that is, diminished effectiveness of insulin in reducing blood glucose levels. "Additionally, different studies have proposed potential DNA methylation biomarkers in relation to plasma insulin levels, insulin secretion and insulin resistance such as those located in PPARGC1A, HTR2A, LY86, TFAM, GIPR, ADIPOQ, and IGFBP3 genes." (PMID 31208038, 2019).
atherosclerosis (3 papers, 2022 to 2024). A disease characterized by the build-up of fatty material and calcium deposition in the arterial wall resulting in partial or complete occlusion of the arterial lumen. "This study demonstrates the involvement of LY86 in atherosclerosis development, with high expression observed in human plaque tissues." (PMID 38822281, 2024). "In our study, we collected common carotid artery plaque tissues and observed an up-regulation of LY86 expression in atherosclerosis." (PMID 38822281, 2024). "Firstly, we confirmed that LY86 is indeed involved in the process of atherosclerosis and found high expression levels of LY86 in human atherosclerotic plaque tissue." (PMID 38822281, 2024). "Several studies have reported significant up-regulation of LY86 mRNA in atherosclerosis; nevertheless, the regulatory mechanism by which LY86 is involved in this disease remains unclear." (PMID 38822281, 2024). "However, the precise role of LY86 in atherosclerosis remains incompletely understood." (PMID 38822281, 2024). "Of these, after gene expression verification, only ITGB2, CTSS, LY86, and ITGAX were found to be highly expressed in both atherosclerosis and AAA." (PMID 39560590, 2024).
leukemia (3 papers, 2019 to 2021). A malignant (clonal) hematologic disorder, involving hematopoietic stem cells and characterized by the presence of primitive or atypical myeloid or lymphoid cells in the bone marrow and the blood. "This study tries to determine whether leukemia microvesicles are able to affect healthy HSPCs and dysregulate some genes such as LY86, LRG1 and PDE9A as LSC specific genes which have fully different patterns of expression in HSC and LSC." (PMID 31548916, 2019). "On hematological diseases cellular model, healthy hematopoietic stem progenitor cells overexpressed the leukemia stem cell-specific genes LY86, LRG1, and PDE9A under the induction of leukemia microvesicles." (PMID 35095520, 2021). "Moreover, healthy hematopoietic stem progenitor cells (HSPCs) can be transformed genetically by leukemia macrovesicles to over express LSC specific genes, which contains LY86, LRG1 and PDE9A and so on." (PMID 33604283, 2020).
osteosarcoma (3 papers, 2020 to 2023). A usually aggressive malignant bone-forming mesenchymal neoplasm, predominantly affecting adolescents and young adults. "LY86 was identified as a novel biomarker for the prediction of osteosarcoma prognosis and therapeutic targets." (PMID 33604283, 2020).
Candidemia (2 papers, 2020 to 2022). A form of invasive candidiasis where species of CANDIDA are present in the blood. "LY86 silencing impairs monocyte migration, increasing susceptibility to candidemia." (PMID 36733397, 2022). "Finally, experimental follow-up confirmed that LY86 knockdown results in reduced monocyte migration towards the chemokine MCP-1, thereby implying that this reduced migration may underlie the increased susceptibility to candidemia." (PMID 32251450, 2020).
glioma (2 papers, 2022 to 2024). A benign or malignant brain and spinal cord tumor that arises from glial cells (astrocytes, oligodendrocytes, ependymal cells). "The genes analyzed included HLA‐DQA1, HLA‐DQB1, HLA‐DMB, LY86, MS4A7, FOLR2, and MS4A4A in glioma patients." (PMID 38997808, 2024). "The subsequent correlation analyses also indicated MD2 was strongly correlated with CD14, LY86, TLR1 and TLR4 in gliomas." (PMID 35372062, 2022).
viral infections (2 papers, 2022 to 2025). "Among the 6 genes, over-expressed genes (HK3, DEFA4, BATF) were positively correlated with severity of viral infection, and under-expressed genes (HLA-DPB1, LY86, TGFBI) were negatively correlated with severity." (PMID 35042868, 2022). "Each of the 6 genes were significantly differentially expressed between patients with viral infections who survived and those who did not, of which 3 genes (DEFA4, BATF, HK3) were higher and 3 genes (TGFBI, LY86, HLA-DPB1) were lower in those who died." (PMID 35042868, 2022).
congenital cataracts (1 paper, 2023). "In addition, some researchers have found that the pathogenesis of congenital cataracts caused by TDRD7 deficiency may be related to the immune response, defence response, and related genes LY86, C1QA, C1QB, and C1QC." (PMID 36586009, 2023).
periodontitis (1 paper, 2025). An acute or chronic inflammatory process that affects the tissues that surround and support the teeth. "Periodontitis induced the development of GMPs toward the neutrophil lineage at the expense of monocytic differentiation, as indicated by the dynamic changes in monocytic signature genes (F13a1, Irf8, and Ly86) and neutrophil-associated genes (Camk1d, S100a8, and S100a9) along the trajectory." (PMID 40521205, 2025).
tumor (9 papers, 2020 to 2026). "The downregulated expression of IL-1, CTSW, NR1H3 and CCR8 (with HR < 1) indicated these molecules as tumor suppressors, whereas the upregulated expression levels of LY86, RABGEF1, CYFIP2 and SERINC3 (with HR > 1) indicated these molecules as oncogenes." (PMID 33816214, 2020). "LY86 participates in Toll-like receptor signaling and tumor microenvironment regulation." (PMID 39055563, 2024). "In MSI-high tumors, altered LY86-mediated signaling could contribute to an immunosuppressive microenvironment that favors tumor escape." (PMID 39055563, 2024). "The results indicated an increase in MS4A4A, HLA‐DMB, LY86, MS4A7, and FOLR2 expression in GBM tumor samples compared to normal tissue samples (n = 706)." (PMID 38997808, 2024). "Compared with those in the normal pancreas (GTEx + TCGA), CA9, TNNT1, CCL21, LY86, and CCL19 were all expressed higher in tumor tissues, except for FABP4, which was expressed lower in a tumor (p < 0.001)." (PMID 34777388, 2021). "When comparing our gene expression analyses and genetic analyses, the cancer genes HLA-DPA1, HLA-DMB, DNAJA4, LY86, HCLS1, GABBR1, NUDT16 showed upregulation in tumor tissue compared to cell subpopulations and are located in chromosomal regions that showed losses in GSC and CD133pos./CD15pos. cells." (PMID 32634135, 2020).
infection (8 papers, 2012 to 2025). The state of being infected such as from the introduction of a foreign agent such as serum, vaccine, antigenic substance or organism. "In this manner, genes that encode negative regulators of TLR-mediated signaling, such as TOLLIP (Toll-interacting protein) and the lymphocyte antigen 86 (LY86) known as MD1, were up-regulated 6 h after infection." (PMID 22235359, 2012). "Further analyses at day 140 post-infection uncovered only 3 additional upregulated genes (SCRG1, LY86, SFT2D2) in IFNR−/− mice." (PMID 23737750, 2013).
cancer (7 papers, 2015 to 2022). A tumor composed of atypical neoplastic, often pleomorphic cells that invade other tissues. "These suggests that LY86 might play an important role in the transformation of localized normal bone marrow cells to cancer cells." (PMID 33604283, 2020). "Through further analysis, we found that TYROBP, FCGR2B, TYROBP, LY86, and TLR2 genes were highly expressed in ccRCC carcinoma tissues." (PMID 36595751, 2022).
LY86 also shares sentences with these, for which no sentence is quoted: Duchenne muscular dystrophy (8 papers); heart failure (8); diabetes (4); hypertrophic cardiomyopathy (4); myotonic dystrophy type 1 (4); cardiomyopathy (3); fibrosis (3); muscular dystrophy (3); Anxiety (2); cardiovascular diseases (2); colitis (2); dilated cardiomyopathy (2); lupus (2); melanoma (2); metabolic disorders (2); muscle disorders (2); Myocardial fibrosis (2); Myotonia (2); myotonic dystrophy (2); neuromuscular disease (2); type 2 diabetes (2); acute myeloid leukemia (1); amyotrophic lateral sclerosis (1); Arrhythmia (1); autoimmune disease (1); bone metabolic disorders (1); Brachycephaly (1); breast carcinoma (1); cardiac diseases (1); ciliopathy (1).
A further 45 diseases each share a sentence with LY86 in 1 paper.